GSN (gelsolin)
Diseases named in the same sentence as GSN in open-access papers (continued):
Sharing a sentence is not in itself a finding about the gene and the disease.
liver failure (1 paper, 2017). A liver disease characterized by the liver losing or has lost all of its function. "Moreover, research in animal models have already been carried out and an in vivo study in liver failure mice showed that cGSN is increased during the disease process, and a significantly higher number of apoptotic cells are found in the liver of GSN knockout mice." (PMID 28377587, 2017).
mastitis (1 paper, 2020). Inflammation of breast tissue during lactation or postpartum due to an obstructed duct or infection. "For example, GSN has been suggested as indicator of mastitis and many studies have documented important function of SOCS2 in the regulation of cytokines and mastitis." (PMID 32754201, 2020).
metastasis (1 paper, 2022). The spread or migration of cancer cells from one part of the body (where they first appeared) to another. "We found that Gelsolin and PRDX4 are linked together, whose levels are influenced as a prognostic and predictive biomarker in CRC tumor tissues with lymph node metastasis (LNM) stage IV." (PMID 35804959, 2022).
myocardial ischemia (1 paper, 2012). A disorder of cardiac function caused by insufficient blood flow to the muscle tissue of the heart. "Among them, four glycolytic enzymes, L-LDH, GAPDH, GPI, PGAM2, and two targets of MMP, gelsolin and isoform 8 of titin, are significantly released into the effluent during myocardial ischemia." (PMID 22443514, 2012).
nasopharyngeal carcinoma (1 paper, 2017). A carcinoma arising from the nasopharyngeal epithelium. "In our previous study, five different secretory proteins, including GSN, ADAMTSL4, CALR, PPIA and TXN, have been identified to be associated with the nasopharyngeal carcinoma (NPC) metastasis." (PMID 28107202, 2017).
neuropathic pain (1 paper, 2022). Chronic pain caused by damage to nerve fibers. "Synaptic proteins such as gelsolin, apolipoprotein C1, apolipoprotein E, contactin-1, and neural cell adhesion molecule L1-like protein were altered in cerebrospinal fluid of neuropathic pain patients and contributed to pain treatment." (PMID 36545122, 2022).
oral squamous cell carcinoma (1 paper, 2023). "It has been shown that upregulated GSN expression contributes to cell proliferation, migration and invasion in human oral squamous cell carcinoma Tca8113." (PMID 37958747, 2023).
ovarian disease (1 paper, 2023). "It has been described that gelsolin is also associated with ovarian disease in humans, and GSN has been identified as a marker for these disease processes." (PMID 37550786, 2023).
pancreatic ductal adenocarcinoma (1 paper, 2021). An infiltrating adenocarcinoma that arises from the epithelial cells of the pancreas. "Interestingly, it was recently proven that GSN interacts with cortactin in human pancreatic ductal adenocarcinoma cells (PDAC), though the authors showed GSN co-localization with cortactin at the cell periphery and not in invadopodium." (PMID 34440617, 2021).
parvovirus infection (1 paper, 2008). "Altogether, these observations point to lipid-dependent signaling as a potential alternative gelsolin target to be studied for its impact on the outcome of parvovirus infection." (PMID 18704167, 2008).
periodontitis (1 paper, 2025). An acute or chronic inflammatory process that affects the tissues that surround and support the teeth. "Previous studies have reported heterogeneity in gingival fibroblasts in periodontal tissues, with four subsets significantly altered in periodontitis: Fib 1.1 (CXCL1, CXCL2, CXCL13); Fib 1.2 (APCDD1, IGFBP2, MRPS6); Fib 1.3 (APOD, GSN, CFD); and Fib 1.4 (TIMP3, ASPN, COL11A1)." (PMID 40801798, 2025).
polyp (1 paper, 2023). A usually exophytic mass attached to the underlying tissue by a broad base or a thin stalk. "In conclusion, our study identified an association between the increased expression of CDC42, TAGLN, and GSN in high-risk polyps, suggesting a potential role in polyp malignancy." (PMID 37365287, 2023).
psoriasis (1 paper, 2023). An autoimmune condition characterized by red, well-delineated plaques with silvery scales that are usually on the extensor surfaces and scalp. "In conclusion, low serum gelsolin levels are associated with the severity of psoriasis, proposing the potential role of gelsolin as a biomarker for severity assessment and evaluation of treatment response of psoriasis." (PMID 36902587, 2023). "We then investigated the correlation of gelsolin levels with severity scores in the group of patients with psoriasis." (PMID 36902587, 2023). "Second, although it is a concern that has always been raised in the field of biomarker research, it was ambiguous to draw a definitive conclusion regarding changes in gelsolin preceding or following progression of psoriasis." (PMID 36902587, 2023). "Subsequent validation study with ELISA was completed initially by comparing gelsolin levels in psoriasis and control groups." (PMID 36902587, 2023). "Comparing the biomarker levels between control and psoriasis subgroup after adjusted for age and sex, it was demonstrated that gelsolin level was lower in the pre-treatment psoriasis group than in the control and post-treatment group." (PMID 36902587, 2023). "Our study is to discover gelsolin as a candidate protein in psoriasis through proteomic research and then validate it as a potential novel biomarker." (PMID 36902587, 2023). "In those with psoriasis, baseline gelsolin level was significantly lower than that at 16 weeks post-treatment (57.28 ± 33.27 ng/mL, p < 0.05) and 52 weeks post-treatment (78.01 ± 32.91 ng/mL, p < 0.01)." (PMID 36902587, 2023). "In summary, we identified gelsolin as a potential clinical biomarker of psoriasis based on 2-DE and LC-MS/MS analysis." (PMID 36902587, 2023). "We subsequently analyzed the relationship between clinical scores and gelsolin levels in psoriasis patients." (PMID 36902587, 2023). "Serum gelsolin levels were lower in the groups of psoriasis patients before treatment than in the control group and the group of psoriasis patients after treatment." (PMID 36902587, 2023). "Few studies have been conducted on the implication of gelsolin in the development and progression of psoriasis." (PMID 36902587, 2023). "However, one study has suggested that gelsolin is a protein marker of PsA, not only for screening PsA but also for differentiating between psoriasis and PsA." (PMID 36902587, 2023). "We obtained results that show gelsolin could serve as a potential biomarker of clinical severity and therapeutic response in psoriasis, in accordance with comparative proteomic data analysis and identification and validation through measurement of serum gelsolin levels." (PMID 36902587, 2023).
psoriatic arthritis (1 paper, 2023). Joint inflammation associated with psoriasis. "We studied whether there was a difference in baseline gelsolin level between patients with and without psoriatic arthritis (PsA) or nail changes." (PMID 36902587, 2023).
pulmonary hypertension (1 paper, 2022). Increased pressure within the pulmonary circulation due to lung or heart disorder. "The avoidance of pulmonary hypertension is due to the increased expression of GNG2 and CA2 and the decreased expression of TAGLN and MPO, and the increased vascular permeability is due to the increased expression of GNG2 and the decreased expression of GSN." (PMID 36009723, 2022).
renal carcinoma (1 paper, 2022). A carcinoma arising from the epithelium of the renal parenchyma or the renal pelvis. "In addition, Ki-67 can be used in combination with other markers such as MCM-2, survivin, B7-H1, geminin, carbonic anhydrase, IX, gelsolin, MIB-1, and phosphorylated S6 protein, and the interaction between white (pS6) and vimentin affects the prognosis of renal cancer." (PMID 35741311, 2022).
renal clear cell carcinoma (1 paper, 2022). "However, the downregulation of gelsolin in renal clear cell carcinoma has been reported to be indicative of worse prognosis." (PMID 34144901, 2022).
rotator cuff tear (1 paper, 2018). "There were 2 common genes, namely, Rps6kb1 and gelsolin, which displayed commonly regulated expressions in the 3 categories (aging, apoptotic process, and muscle atrophy) of our interest that are known to be associated with muscle degeneration and atrophy after a rotator cuff tear." (PMID 30671462, 2018).
squamous cell carcinoma of the larynx (1 paper, 2022). "This research is the first to demonstrate that Gelsolin expression is associated with a poor prognosis in laryngeal squamous cell carcinoma." (PMID 34144901, 2022). "Gelsolin is a novel promising biomarker and attractive target for the treatment of laryngeal squamous cell carcinoma." (PMID 34144901, 2022). "Our aim is to investigate the clinicopathological significance of gelsolin as a prognostic biomarker for laryngeal squamous cell carcinoma." (PMID 34144901, 2022). "Altered gelsolin expression has been reported in several types of neoplasms, but clinicopathological features of gelsolin are currently unclear in patients with laryngeal squamous cell carcinoma." (PMID 34144901, 2022).
synovitis (1 paper, 2025). Inflammation of a synovial membrane. "For Thoroughbreds, gelsolin concentrations were lower for higher OA grades, and afamin was lower at a higher synovitis grade." (PMID 39972657, 2025).
T-cell lymphoma (1 paper, 2018). "Our findings might contribute to the current understanding of the biological functions of GSN in NK/T-cell lymphoma." (PMID 29175858, 2018). "Although the roles of GSN have been explored, whether the GSN can modulate cell proliferation, apoptosis and invasion in NK/T-cell lymphoma cells is currently unknown." (PMID 29175858, 2018). "Further investigations are required concerning the role of GSN in NK/T-cell lymphoma progression to determine whether decreased or increased GSN levels in NK/T-cell lymphoma have a direct relationship with tumorigenesis." (PMID 29175858, 2018).
thrombotic disease (1 paper, 2019). The formation of a blood clot in the lumen of a vessel or heart chamber; causes include coagulation disorders and vascular endothelial injury. "Though gelsolin replacement therapy (GRT) has been shown to be effective in some animal models, no such study has been reported for thrombotic diseases that are acutely in need of bio-therapeutics for immediate and lasting relief." (PMID 31002695, 2019).
transitional cell carcinoma (1 paper, 2020). A malignant neoplasm arising from the transitional epithelium, usually affecting the urinary bladder, ureter, or renal pelvis. "Based on betweenness centrality and survival analysis, we identified laminin subunit gamma-2 (LAMC2) in the grade 2 carcinoma, gelsolin (GSN) in the grade 3 carcinoma, and homeodomain-interacting protein kinase 2 (HIPK2) in the transitional cell carcinoma lymphatic metastasis." (PMID 32640634, 2020). "According to the results of the betweenness and survival analysis in four disease types, LAMC2, GSN, and HIPK2 may respectively be the potential regulator in cell lines with grade 2 carcinoma, grade 3 carcinoma, and transitional cell carcinoma lymphatic metastasis." (PMID 32640634, 2020).
Trypanosoma cruzi infection (1 paper, 2018). "One report suggested potential utility of increased plasma levels of gelsolin in diagnosing disease severity and evaluating efficacy of therapeutic treatments during Trypanosoma cruzi infection and Chagas disease." (PMID 30149613, 2018).
TTR amyloidosis (1 paper, 2022). "TTR amyloidosis is the most prevalent and well-characterized of the three major forms of familial amyloid polyneuropathy, the others being apolipoprotein A1-associated and gelsolin-associated amyloid neuropathy." (PMID 36341129, 2022).
tuberous sclerosis (1 paper, 2018). Hereditary disease characterized by seizures, intellectual disability, developmental delay, and skin and ocular lesions. "Another study reported that stress-induced ATF3–Gelsolin cascade is responsible for spine deficits in the tuberous sclerosis complex." (PMID 29515366, 2018). "Knocking down ATF3 expression with shRNA decreased Gelsolin expression and increased dendritic spine density in neuronal models of tuberous sclerosis complex." (PMID 29515366, 2018).
type 2 diabetic nephropathy (1 paper, 2019). "In these preliminary discovery experiments, we first implemented the iTRAQ technique to identify plasma gelsolin, collectin-11, PTPRJ, and AKAP-7 as candidate biomarkers in type 2 IDN, which will provide a useful basis for further analysis of the pathogenic mechanism of type 2 diabetic nephropathy." (PMID 31384238, 2019).
urothelial carcinoma (1 paper, 2024). A malignant neoplasm derived from the transitional epithelium of the urinary tract (urinary bladder, ureter, urethra, or renal pelvis). "For example, Rao and colleagues (2002) reported decreased gelsolin expression in the early stages of malignant transformation in urothelial carcinomas." (PMID 39061201, 2024). "However, there was an increase in gelsolin expression in the transition from non-invasive to invasive urothelial carcinomas, indicating a biphasic expression pattern." (PMID 39061201, 2024).
tumor (118 papers, 2003 to 2025). "This study identifies a novel integrin binding competition between pGSN and TNC, and GSN gene methylation during ESCC tumor progression causes decreased secretion of pGSN, leading to integrin αvβ3 dysregulation, oncogenic TNC activation, and CAF formation." (PMID 39261905, 2024). "GSN was tightly associated with the immune and inflammatory response, cell proliferation and cell migration, which are key steps for tumour progression." (PMID 38803199, 2024). "These include exosome-containing oncogenic proteins, such as STAT3 and FAS, microRNAs that altered tumor-associated macrophages, as well as plasma gelsolin, which induces the conversion of chemosensitive OC cells to chemoresistant cells." (PMID 38403587, 2024). "When analyzing tumor-infiltrating immune cells, gelsolin was linked to the level of infiltration seen and indispensable for those immune cells to infiltrate the tumors." (PMID 37373424, 2023). "Our analysis showed a strong association between histopathological tumor grade and expression of gelsolin." (PMID 34144901, 2022). "There was a strong association between expression of gelsolin and tumor stage, tumor differentiation, tumor recurrence, and Lymphovascular Invasion (LVI), with p-values of 0.001, 0.031, 0.018 and 0.016 respectively." (PMID 34144901, 2022). "Gelsolin expression is significantly associated with tumor stage, tumor grade, and locoregional recurrence." (PMID 34144901, 2022). "In other words, they realized that Gelsolin overexpression was notably associated with more invasive tumor behavior and higher cancer mortality rates." (PMID 33391377, 2021). "In this study, our findings suggest that the overexpression of GSN is associated with an aggressive tumour phenotype and a poor prognosis in HCC patients after hepatectomy." (PMID 32377190, 2020). "Previous studies have also shown that GSN is involved in the regulation of tumour metastasis, but the association is unclear." (PMID 32377190, 2020). "Although gelsolin has been reported to overexpress and induce tumor invasion in CRC cases, the role and the association of CapG with CRC are still unclear." (PMID 30155403, 2018). "Pathology studies further demonstrated that the overexpression of gelsolin in patients with PCa was associated with significantly higher incidence of early tumor recurrence and metastasis, as well as reduced patient survival." (PMID 29100377, 2017). "Three PCa cell lines, PC3, DU145 and LNCaP, were examined by western blotting for the expression of gelsolin and the other tumor-associated proteins." (PMID 29100377, 2017). "Loss of gelsolin, a tumor suppressor, is one of the most frequently occurring molecular defects in breast cancers of diverse etiologies in human, mouse, and rat10." (PMID 28993697, 2017). "The tumor suppressive role of gelsolin is mostly linked to its downregulation in several cancers including breast, colon, stomach, bladder, prostate, lung as well as in transformed human fibroblast and epithelial cells." (PMID 27391159, 2016). "The reason for focusing on this specific protein derives from the fact that loss of gelsolin is one of the most frequently occurring molecular defects in BC and it negatively correlates with tumor progression." (PMID 26061043, 2015). "Initial evidence of anti-apoptotic effect of gelsolin was provided by the observation that a point mutation in mouse gelsolin confers on this protein tumor-suppressor activity against H-ras oncogene transformed NIH-3t3 cells." (PMID 24367717, 2013). "Collectively, our results indicate that overexpression of gelsolin in PC10 cells causes tumour suppression in nude mice through inhibiting the activation of PKCs by sequestering PIP2, which is a substrate of PLC." (PMID 12592377, 2003). "Furthermore, increased gelsolin activation has been associated with tumor metastasis in various cancers." (PMID 40106086, 2025). "Secreted gelsolin is linked to the inhibition of anti-tumor immune mechanisms and tumor immunity." (PMID 35419364, 2022).